BDNF (brain derived neurotrophic factor)
Diseases named in the same sentence as BDNF in open-access papers (continued):
Sharing a sentence is not in itself a finding about the gene and the disease.
depression (continued). "Furthermore, the beneficial effects of curcumin on long-term depression and anxiety have been linked to the upregulation of the brain-derived neurotrophic factor (BDNF) and the reduction of inflammatory factors in the brain." (PMID 40551742, 2025). "Moreover, neuroinflammation-induced depression-like behaviors in mice has been linked to reduced hydroxymethylation of BDNF gene and elevated expression of Iba-1, a marker for microglia activation, in the hippocampus region." (PMID 40643545, 2025). "In recent years, the possibility of using serum BDNF concentrations and/or studying BDNF gene polymorphisms as indicators of neuroplasticity and as potential peripheral biomarkers of depression and patients’ response to antidepressant therapy has been widely explored." (PMID 40869303, 2025). "Recent studies have provided strong evidence that the loss of neurons is a key factor in depressive disorders, and antidepressant treatment increases the expression of BDNF in the granule layer of the hippocampal DG, thereby contributing to the regulation of stress and antidepressant neurogenesis." (PMID 40149758, 2025). "Finally, individual variability and genetic differences in patients, particularly variations in genes associated with BDNF production or its receptor or in the pathophysiology of depression, can influence how BDNF levels are regulated in different patients." (PMID 40565369, 2025). "Depression is characterized by various physiological processes, such as vascular disease, alterations in glucocorticoid signal transduction, hippocampal atrophy, brain inflammation, and deficiencies in BDNF." (PMID 38985081, 2024). "The neurotrophic factor hypothesis indicates that a decrease in BDNF in the cortical and limbic regions of the brain is associated with depression." (PMID 37581520, 2024). "Therefore, the prolonged oxidative stress led to increased PDE4 which in turn decreased CERB, PRKACA and BDNF and increased IL-6, enhancing neuronal susceptibility to injury and development of depression." (PMID 38315652, 2024). "Thus, there is strong evidence that at least BDNF is associated with increased risk for depression, whereas increasing BDNF by exercise appears to improve memory function and to reduce depression." (PMID 39194496, 2024). "Although reduced serum BDNF levels have been linked to be associated with an increased risk of developing major depression and suicidal ideation, findings are inconsistent across all studies, and the underlying mechanisms remain unclear." (PMID 39474368, 2024). "In summary, this study demonstrates that SNPs of the microRNA146a gene at rs2910164, ACE2 gene at rs2285666 and the SGK1 gene at rs1743963 and rs1763509, and the SNPs at the 5-HTTLPR and BDNF gene loci are associated with the onset of comorbid depression in coronary heart disease." (PMID 38745947, 2024). "A decrease in BDNF levels is associated with the development of depression." (PMID 39479195, 2024). "Many studies discuss multiple common pathological mechanisms involved in obesity and depression like chronic systemic inflammation, the dopaminergic reward system, vitamin D deficiency and neuroendocrine mechanisms via leptin melanocortinergic—BDNF signaling." (PMID 38523835, 2024). "Consequently, reductions in BDNF levels are associated with cellular atrophy in the prefrontal cortex and hippocampus—areas strongly linked to depression." (PMID 39796528, 2024). "Therefore, BDNF is a crucial agent for neurogenesis and synaptic plasticity and, unsurprisingly, is reported to be associated with changes in anxiety and depression." (PMID 39684635, 2024). "Therefore, BDNF and its association with depression in cancer patients is an important area of research that can contribute to the understanding and treatment of depression in this population." (PMID 39355088, 2024). "BDNF deficiency causes neuroinflammation, which can lead to symptoms of major depressive disorder." (PMID 39519391, 2024).
depression (continued). "In addition, decreased BDNF levels, especially in the hippocampal area, in ovariectomized female rats are thought to be associated with depression‐like behavior." (PMID 39443283, 2024). "This suggests that higher levels of hippocampal BDNF expression may be associated with diminished depression-like behaviors." (PMID 39766310, 2024). "In addition to the general role of BDNF in depression, genetic variations such as the Val66Met polymorphism have been identified as potential vulnerability factors, particularly in the context of inflammation." (PMID 39355088, 2024). "This inconsistency has led to calls to revisit the original hypothesis that the hypofunctioning BDNF Met‐alleles serve as biological risk factors for depression and other forms of psychiatric illness or ill‐being." (PMID 38997217, 2024). "In addition to BDNF, depression and neurodegeneration are associated with other decreased neurotrophic factors, like neurotrophic factor-α1 (NF-α1) and nerve growth factor." (PMID 38038373, 2024). "Our results suggest that cancer-related fatigue predicts depression, especially in participants with the BDNF Met/Met genotype, and the relationship between the BDNF polymorphism and depression appears to be mediated by cancer-related fatigue in our population of female cancer survivors." (PMID 37462904, 2024). "Studies have found that increased methylation of BDNF gene is associated with depression." (PMID 39130405, 2024). "Notably, BDNF has been implicated in the pathophysiology of various neurological and psychological disorders, including depression." (PMID 39478958, 2024). "Depression is linked with oxidative stress and inflammation, where key players include nitric oxide (NO), nuclear factor erythroid 2-related factor 2 (Nrf2), Brain-Derived Neurotrophic Factor (BDNF), and Heme Oxidase-1 (HO-1)." (PMID 38180676, 2024). "Despite these findings as well as the notion that late-life depression and depressive symptoms may represent a prodromal feature of AD, the association between BDNF and NPS has rarely been studied in the context of AD." (PMID 38279143, 2024). "In individuals with depression, reduced BDNF levels, particularly in critical brain regions such as the hippocampus and prefrontal cortex, correlate with the atrophy observed in these regions, a hallmark of depression." (PMID 39568824, 2024). "Studies have shown that BDNF may be involved in the pathological processes underlying depression in PD patients, thereby playing a significant role in cognitive function and depression." (PMID 39648800, 2024). "Furthermore, dysregulation of BDNF functions has been implicated in some diseases such as depression, chronic pain, and neurodegenerative conditions." (PMID 38254671, 2024). "Subsequently, the increase of inflammatory cytokine levels causes BBB destruction, the dysfunction of neurotransmitters such as 5-HT, DA, NE, GABA and Glu, BDNF deficiency and dysfunction, and attenuation of neuroplasticity, which are key factors in the onset and progression of depression." (PMID 38898454, 2024). "The ratio of BDNF to leptin levels has been associated with treatment responses in depression and may also be related to the neuroplasticity of depression, as evidenced by a 12-week follow-up study." (PMID 39253375, 2024). "The detection of circulating BDNF levels has become an area of great interest in recent years due to their association with various neuropsychiatric disorders such as Parkinson's disease, autism spectrum disorder, depression, and Alzheimer's disease." (PMID 39224579, 2024). "The aim of our study was to assess whether serum levels of NfL and BDNF are associated with the risk of depression in ESKD patients." (PMID 38255209, 2024). "Lower BDNF levels have been linked with chemotherapy-related cognitive impairment but the association with depression in cancer patients remains unclear." (PMID 39355088, 2024).
depression (continued). "Moreover, we focused on studies investigating the brain-derived neurotrophic factor (BDNF) as a functional target of miR-206, where miR-206 has been implicated in the pathogenesis of depression by suppressing the expression of the BDNF." (PMID 39219169, 2024). "The neurotrophic hypothesis of depression proposes that stress triggers a reduction in BDNF expression within crucial limbic structures, which are also implicated in the pathogenic mechanisms of depression." (PMID 38541632, 2024). "The neurotrophic factor hypothesis posits that the deficiency of neurotrophic factors, such as BDNF, leads to a decline in neural plasticity, thereby playing a significant role in the onset and progression of depression." (PMID 39882216, 2024). "Previous hypotheses suggest that deficiencies in neurotrophic support, including impaired BDNF function, could be a significant factor contributing to depression, leading to pathological deterioration and behavioural decline." (PMID 39656488, 2024). "Therefore, the Met allele, which is responsible for reduced BDNF availability, is considered by many researchers to be a risk factor for psychopathology, including increased neuroticism, anxiety, depression, and suicide." (PMID 38255861, 2024). "Additionally, we evaluated the role of the SNP sites of HTR1A, HTR1B, S100A10, BDNF genes in depression patients through genetic association analysis." (PMID 39130405, 2024). "Furthermore, an experimental study showed that corticosterone-induced depression is mediated by autophagy hyperactivation and associated reduction of BDNF by excessive lysosomal degradation." (PMID 38006577, 2024). "Previous studies have shown that decreased serum BDNF levels in patients may be predictive of major depression and that increased BDNF levels are associated with antidepressant effects." (PMID 39062817, 2024). "Modern research has shown that the anti‐depression effect of ZZCD might be associated with PKA/CREB/BDNF/TrkB/PSD‐95 pathway influenced by metabolic changes." (PMID 37905694, 2024). "In addition, another possible biological mechanism is the modulation of brain-derived neurotrophic factor (BDNF), which is linked to the development of depression." (PMID 40226658, 2024). "The primary biological mechanism through which exercise mitigates depression involves the stimulation of several neuroregenerative processes associated with depression, such as the hippocampus, brain-derived neurotrophic factor (BDNF), and dopamine." (PMID 39469239, 2024). "Reports have indicated that the abnormal activity of BDNF in individuals with depression may be partially caused by changes in bile acid activity." (PMID 38357350, 2024). "In major depressive disorder (MDD), BDNF may work by limiting the translocation of bacteria and their components, such as LPS associated with depression by previous studies." (PMID 39596179, 2024). "Similarly, elevated miR-202-3p levels in the hippocampus have been linked to diminished BDNF expression in a CUMS-induced depression model." (PMID 38474112, 2024). "For instance, the serum level of BDNF could be altered by comorbid depression, SSRIs, or SNRIs, and underlying hidden neurodegenerative diseases that have not yet manifested." (PMID 38671372, 2024). "A leaky gut can allow microbial products such as LPS to trigger inflammatory reactions via proinflammatory cytokines that can cross the BBB leading to disrupted brain activity implicated in major depressive disorder via modulation of BDNF, kynurenine, and serotonin signaling pathways." (PMID 39470120, 2024). "Hence, it seems plausible that decreased methylation of the BDNF exon IV promoter constitutes a biomarker of adolescent depression state as well as susceptibility." (PMID 38542252, 2024). "Physical activity is found to increase the brain blood flow, thereby increasing the synthesis and release of BDNF, indicating that physical activity may reduce the risk of depression by increasing BDNF concentrations." (PMID 39949496, 2024).
depression (continued). "Elevated levels of inflammatory mediators could lead to a reduction in brain-derived neurotrophic factor, which negatively influences neurogenesis and neuroplasticity and is also associated with depression." (PMID 37848651, 2024). "Among the SNP studies on BDNF associated with depression, the most reported and studied is rs6265 (Val66Met), and some studies have shown that the BDNF Val66Met polymorphism correlates with serum BDNF levels and can be used as a predictor of major depressive disorder." (PMID 37581520, 2024). "However, a 2013 meta-analysis found an association between BDNF rs6265 and depression, and a 2010 meta-analysis reported an increased risk of depression among male Met carriers." (PMID 37462904, 2024). "The Val66Met polymorphism of the BDNF gene is associated with depression." (PMID 38745947, 2024). "Considering the significant role of BDNF in the pathogenesis of depression, dysregulation of BDNF-associated miRNAs may also be closely linked to depression." (PMID 38404466, 2024). "BDNF is a molecule associated with neuroplasticity and is believed to play an important role in regulating neural development, and is involved in the pathological and physiological progression of depression." (PMID 39367470, 2024). "The importance of BDNF is that it may promote neuronal survival, axonal guidance, and activity-dependent synaptic plasticity, and it may be associated with depression." (PMID 38921661, 2024). "Some previous data showed, in fact, that depressed patients have lower BDNF plasma levels than controls, suggesting that plasma BDNF may parallel central BDNF and may be associated with clinical features of major depressive disorder." (PMID 38542503, 2024). "Alteration of pro- and mature BDNF signaling during the early postnatal period could have a long-lasting outcome on mental health and predisposition to anxiety and depression in adulthood." (PMID 39619203, 2024). "Long-term exposure to work-related stress can cause depression, and BDNF polymorphism may play a significant role in this process." (PMID 38252222, 2024). "It is speculated that there could be an association between microglial polarization and BDNF/TrkB/CREB signaling in the context of depression." (PMID 38337722, 2024). "Several lines of evidence suggest that the BDNF rs6265 polymorphism could be involved in depression." (PMID 39565757, 2024). "On the contrary, meditation interventions efficiently reduce cortisol levels; the reduction in cortisol was found in another study to be associated with improvements in serum BDNF levels and depression scores through yoga, which is suggested to be a facilitator of neuroplasticity." (PMID 39684635, 2024). "Furthermore, gut microbiota -mediated inflammation is strongly associated with the development of depression through the downregulation of BDNF expression involved in NF-κB activation." (PMID 39494347, 2024). "Both AUDs and depression are associated with a depletion of serum BDNF levels, which might indicate a common pathway in their physiopathology." (PMID 39430530, 2024). "Recent research has further linked BDNF/TrkB signaling to depression." (PMID 38835076, 2024). "Other efforts to identify BDNF regulatory regions combined genetic association analysis with comparative genomics to explore the effects of a polymorphism (rs12273363) associated with major depressive disorder (MDD) on BDNF promoter IV activity." (PMID 38228888, 2024). "Our study found an abnormal expression of β-catenin and BDNF, both associated with depressive disorders, suggesting that the downregulation of β-catenin and BDNF in the IL region may be involved in the pathogenesis of PPD." (PMID 38743109, 2024). "Both classes of drugs stimulate AMPARs by increasing extracellular glutamate levels and elevate BDNF levels in brain areas implicated in depression, facilitating the adaptive rewiring of pathological neurocircuitry and explaining their sustained therapeutic effects." (PMID 37997979, 2023).
depression (continued). "However, the already-mentioned study from Russia showed an association between the BDNF gene variant rs6265 and the severity of depression." (PMID 37626739, 2023). "Knockdown of BDNF in the dentate gyrus precipitates behaviors associated with depression." (PMID 37047638, 2023). "We also discovered that gut microbiota from Sig-1R-deficient mice may induce depression-like behaviors through regulation of the cAMP/CREB/BDNF signaling pathway." (PMID 37089558, 2023). "Moreover, isorhamnetin enhanced antidepressant effects of escitalopram and effectively restored depleted levels of Nrf2, BDNF, and HO-1 in the cortex caused by LPS-induced depression." (PMID 37754268, 2023). "In addition, in the case of patients with acute coronary syndrome, the risk of depression was higher in patients with lower BDNF serum levels (OR, 4.60; 95% CI, 1.12–18.97; p = 0.035)." (PMID 37895349, 2023). "Given this evidence, it is possible that BDNF may be associated with the risk for depression in HIV." (PMID 37693812, 2023). "Sleep deficiency may also cause biological changes, including changes in brain-derived neurotrophic factor, which is associated with depression." (PMID 38312139, 2023). "The literature suggests that depression pathogenesis is closely linked with BDNF, and treatment with antidepressant drugs can effectively improve BDNF reduction due to depression, stimulating neurogenesis, increasing neural plasticity and serving as an antidepressant." (PMID 37799103, 2023). "In conclusion, NHQXW has antidepressant effects against chronic stress-associated depression and its underlying mechanisms could be at least in part correlated with its neurogenesis-promoting effects through activating the BDNF/TrkB/ERK/CREB signaling pathway." (PMID 38273824, 2023). "Nonetheless, as depression and recovery from depression have been linked to improved neuronal connectivity, inflammation, and neurotrophic factors, such as the BDNF-pathway, we expect these signals to be represented in our pathway analysis." (PMID 37664245, 2023). "In addition, the administration of microbiota-derived short-chain fatty acids to mice alters the expression of brain-derived neurotrophic factor (BDNF), a neuronal factor associated with depression." (PMID 38033588, 2023). "The role of exercise in depression has been also linked to the BDNF pathway and a variety of immuno-inflammatory mechanisms similar to those specifically described for the adaptogenic herbal extracts in relation to the stress-protective activity and increased adaptability of the organism." (PMID 37047914, 2023). "BDNF is recognized for its vital involvement in numerous cognitive processes and has been linked to several psychiatric and neurological conditions, including major depression disorder, anxiety disorders, schizophrenia, and neurodegenerative diseases." (PMID 37631295, 2023). "Taken together, NHQXW could regulate the BDNF/TrkB/ERK/CREB pathway to induce hippocampal neurogenesis in chronic stress-associated depression." (PMID 38273824, 2023). "Some researchers suggest that ghrelin also affects neuroplasticity, in which abnormalities are intimately associated with depression and may be linked to variations in neurotrophic factor levels, particularly BDNF." (PMID 37764744, 2023). "A decrease in the normal functioning of BDNF has been associated with depression." (PMID 38017532, 2023). "Recent studies have highlighted the association between the HPA axis and BDNF, highlighting the impact of corticosterone on BDNF levels and behavior in animal models, being extremely important in the context of major depressive disorder comprehension and treatment." (PMID 37631295, 2023). "Moreover, BL NCC3001 restored, back to control values, the infection-induced reduction in expression of the hippocampal mRNA levels of brain-derived neurotrophic factor (BDNF), a neurotrophin linked to depression and stress." (PMID 37513541, 2023).